PRMT5 (protein arginine methyltransferase 5)
Diseases named in the same sentence as PRMT5 in open-access papers (continued):
Sharing a sentence is not in itself a finding about the gene and the disease.
pancreatic cancer (continued). "Next, we performed immunohistochemical staining to measure the expression status of PRMT5 in pancreatic cancer patients, and our results demonstrated that PRMT5 expression was significantly higher in PDAC tumor samples than in adjacent normal tissues." (PMID 30922330, 2019). "In conclusion, we identified PRMT5 as a novel marker for predicting the prognosis of pancreatic cancer and reported its novel role in regulating aerobic glycolysis via the FBW7/cMyc axis." (PMID 30922330, 2019). "PRMT5 plays an oncogenic role in pancreatic cancer in various ways." (PMID 40384988, 2025). "Thus, we applied commercial tissue array to detect the expression level of PRMT5 in pancreatic cancer and adjacent normal pancreas." (PMID 40384988, 2025). "Besides, c-Myc inhibitor and PRMT5 inhibitor both suppressed the metastasis induced by TLR3 rescue in the pancreatic cancer liver metastasis model bearing TLR3 knockout cancer cells, reinforcing the non-redundant role of c-Myc/PRMT5 as downstream effectors." (PMID 40675966, 2025). "Interestingly, PRMT5 inhibition induced DNA replication stress in pancreatic cancer, and coadministration of PRMT5 inhibitor with CDC7 inhibitor XL413 exhibited promising therapy value." (PMID 40384988, 2025). "Targeting PRMT5 exhibited promising therapeutic effect for pancreatic cancer." (PMID 40384988, 2025). "By forming a positive feedback loop with c‐Myc, PRMT5 promoted the pancreatic cancer tumorigenesis." (PMID 40384988, 2025). "By promoting the EMT, PRMT5 enhanced metastasis capability of pancreatic cancer." (PMID 40384988, 2025). "Furthermore, the identification of RPA2 as a possible driver of the response to PRMT5 inhibition will require further research in pancreatic cancer." (PMID 40723820, 2025). "PRMT5 inhibition also improved sensitivity to palbociclib in pancreatic cancer." (PMID 40384988, 2025). "In the present study, we investigated the effect of PRMT5 on cell cycle in pancreatic cancer." (PMID 40384988, 2025). "Accumulating evidence suggested that PRMT5 functioned as an oncogenic role in pancreatic cancer." (PMID 40384988, 2025). "Additionally, high levels of TLR3, PRMT5 and c-Myc transcripts were correlated with reduced survival rates in pancreatic cancer patients." (PMID 40675966, 2025). "Furthermore, this study provides a rationale for a clinical regimen that blocks PRMT5-mediated glycolysis in patients with gemcitabine-resistant UBR7-depleted pancreatic cancer." (PMID 39424627, 2024). "In conclusion, we found that UBR7 is depleted in gemcitabine-resistant PDAC and further found that depleted UBR7 stabilizes PRMT5 to increase pancreatic cancer cell and Treg cell glycolysis, leading to pancreatic cancer progression and an immunosuppressive microenvironment." (PMID 39424627, 2024). "However, our data with the CHLA-15 line, together with reports such as the sensitivity of c-MYC over-expressing pancreatic cancers to PRMT5 inhibition suggest that threshold and context-dependent effects are important in c-MYC-driven cancers." (PMID 39313128, 2024). "We first evaluated the effect of T1-44, a selective PRMT5 inhibitor, in pancreatic cancer." (PMID 36765032, 2023). "In addition, cell colony formation and growth were decreased in the combination treatment group, suggesting that apoptosis plays a major role in effective pancreatic tumor reduction by combination therapy of Vactosertib and PRMT5." (PMID 36765032, 2023). "In addition, the tumorigenicity and aerobic glycolysis of pancreatic cancer is increased by PRMT5, mediating epigenetic silencing of E3 ligase FBW7 with upregulation of c-Myc." (PMID 36765032, 2023). "A recent study has been reported that PRMT5 promotes EMT via EGFR in pancreatic cancer cells." (PMID 33495409, 2021). "In addition, PRMT5 promotes oncogenicity in various solid cancers, including colon, breast, prostate, lung, liver, bone, skin, ovarian, gastric, brain, and pancreatic cancers, among others." (PMID 34685445, 2021).
pancreatic cancer (continued). "To better understand the molecules involved in PRMT5 signalling‐induced pancreatic cancer cells invasion, we identified whether PRMT5 affected MMP2 and MMP9 expression in pancreatic cancer cells." (PMID 31851779, 2020). "It is suggested that PRMT5 is critical for the cell proliferation in pancreatic cancer cells." (PMID 31851779, 2020). "It is suggested that PRMT5 plays a major role on the cell invasion in pancreatic cancer cells." (PMID 31851779, 2020). "Furthermore, the effect of PRMT5 on pancreatic cancer cell migration was determined by transwell migration assay." (PMID 31851779, 2020). "Collectively, these data indicate that PRMT5 may function as an oncogene and is a key mediator in carcinogenesis and progression of pancreatic cancer." (PMID 31851779, 2020). "All these findings suggest that PRMT5 may function as an oncogene and be a candidate for diagnosis and prognosis in pancreatic cancer." (PMID 31851779, 2020). "Thus, PRMT5 expression is elevated in pancreatic cancer patients and indicates a worse prognosis for pancreatic cancer patients." (PMID 30922330, 2019). "Our results demonstrated that PRMT5 could regulate aerobic glycolysis in pancreatic cancer via cMyc instead of HIF1α." (PMID 30922330, 2019). "Therefore, it is necessary to conduct an in-depth study to reveal the roles of PRMT5 in FBW7-related processes with an aim to discover novel strategies for the treatment of pancreatic cancer." (PMID 30922330, 2019). "Collectively, these results suggest that PRMT5 could epigenetically suppress FBW7 expression in pancreatic cancer." (PMID 30922330, 2019). "Collectively, these in vitro and in vivo results demonstrated that PRMT5 could regulate proliferation and tumorigenicity in pancreatic cancer cells." (PMID 30922330, 2019). "Further investigations to determine the roles of PRMT5 in pancreatic cancer might aid the discovery of novel therapeutic targets and improve the prognosis of pancreatic cancer." (PMID 30922330, 2019). "Based on the important roles of PRMT5 in pancreatic cancer, trials to test the efficacy of these inhibitors might provide novel strategies for the treatment of pancreatic cancer." (PMID 30922330, 2019). "However, the relevant roles of PRMT5 in aerobic glycolysis that sustain pancreatic cancer tumorigenicity have seldom been discussed." (PMID 30922330, 2019). "However, the importance of the major downstream target of CDKN2A deletion, PRMT5, in pancreatic cancer has seldom been discussed." (PMID 30922330, 2019). "In the present study, we uncovered novel roles for the PRMT family member PRMT5 in pancreatic cancer and demonstrated that PRMT5 expression could predict overall survival in pancreatic cancer." (PMID 30922330, 2019). "We measured the protein stability of cMyc in PRMT5-silenced pancreatic cancer cells after treatment with the protein synthesis inhibitor cycloheximide (CHX) at 100 μM, which could allow the protein stability of cMyc to be assessed." (PMID 30922330, 2019). "The results of in vitro cell line studies and in vivo subcutaneous mouse model experiments demonstrated that PRMT5 could regulate the tumorigenicity of pancreatic cancer cells." (PMID 30922330, 2019). "Moreover, PRMT5 regulated aerobic glycolysis in vitro in cell lines, in vivo in pancreatic cancer patients and in a xenograft mouse model used to measure 18F-FDG uptake." (PMID 30922330, 2019). "The importance of PRMT5 expression in pancreatic cancer has seldom been discussed." (PMID 30922330, 2019). "The PRMT5/FBW7/cMyc axis could be a potential therapeutic target for the treatment of pancreatic cancer." (PMID 30922330, 2019). "Therefore, it is of vital importance to uncover the roles of PRMT5 in pancreatic cancer with an aim to identify novel prognostic and treatment targets." (PMID 30922330, 2019). "Therefore, we speculated that UBR7 regulated glycolysis in pancreatic cancer by regulating the expression of PRMT5, thereby promoting drug resistance." (PMID 39424627, 2024).
pancreatic cancer (continued). "Moreover, PRMT5 epigenetically regulated the expression of FBW7 in pancreatic cancer cells." (PMID 30922330, 2019). "Thus, PRMT5 could potentially regulate aerobic glycolysis both in vitro and in vivo in pancreatic cancer." (PMID 30922330, 2019). "We treated PRMT5-silenced pancreatic cancer cells with the proteasome inhibitor MG132, and the western blotting results demonstrated that MG132 could attenuate the decrease in the cMyc protein level, further confirming the hypothesis that PRMT5 could regulate cMyc at the posttranslational level." (PMID 30922330, 2019). "In addition to isogenic MTAP cell lines, we addressed differential sensitivity between MTAP-proficient and deficient cells towards PRMT5 inhibition in a panel of pancreatic cancer and non-transformed but immortalized cell lines that differ in MTAP status." (PMID 29983885, 2018). "In addition, our study supported with previous publication that PRMT5 could be a novel marker for pancreatic cancer patients’ classification and potential therapeutic target, providing preclinical evidence that PRMT5 could be translated into a therapeutic target for treatment for pancreatic cancer." (PMID 40384988, 2025). "Our main objective in this study was to evaluate the efficacy of PRMT5 inhibition in combination with Gem-based chemotherapy using clinically relevant orthotopic and metastatic PDX mouse models of pancreatic cancer." (PMID 40723820, 2025). "PRMT5 promoted the epithelial–mesenchymal transition (EMT), promoting migration and invasion in pancreatic cancer." (PMID 40384988, 2025). "Particularly, inhibition of PRMT5 reduces the tumor growth via Myc pathway and inhibits epithelial-mesenchymal transition through EGFR-β-catenin axis in pancreatic cancer." (PMID 36765032, 2023). "A previous study has been shown that PRMT5 regulates the autophosphorylation of EGFR at Tyr1068 and Tyr1172 to promotes EMT in pancreatic cancer cells." (PMID 33495409, 2021). "PRMT5 also regulates FBW7 expression and EGFR/β-catenin signaling pathway to promote pancreatic cancer proliferation and tumorigenesis." (PMID 33495409, 2021). "Above all, we for the first time established the link between PRMT5 and EGFR/AKT/β‐catenin signalling in pancreatic cancer." (PMID 31851779, 2020). "Activation of the PRMT5/FBW7/cMyc axis ultimately contributed to enhanced aerobic glycolysis and the sustained proliferation of pancreatic cancer cells." (PMID 30922330, 2019). "Thus, we asked whether PRMT5 could regulate glucose metabolism in pancreatic cancer cells." (PMID 30922330, 2019). "In particular, the PRMT5 inhibitor EZP015556 was shown to target pancreatic tumors negative for MTAP (a gene commonly lost in pancreatic cancer), as well as a subset of MTAP-positive tumors." (PMID 40863456, 2025). "Furthermore, we employed pancreatic cancer tissue microarrays to analyze the expression patterns of TLR3, PRMT5 and c-Myc." (PMID 40675966, 2025). "PRMT5‐mediated methylation suppressed the autophosphorylation and kinase activity of Hippo pathway initiator MST2, resulting in the inactivation of the tumor suppressor pathway Hippo signaling axis and progression in pancreatic cancer." (PMID 40384988, 2025). "PRMT5 was significantly upregulated in pancreatic cancer than adjacent nontumor pancreas, which was positively correlated with poor prognosis." (PMID 40384988, 2025). "Additionally, PRMT5 can suppress the E3 ubiquitin ligase FBXW7 (F-box and WD-40 domain-containing protein 7, also known as FBW7) in pancreatic cancer." (PMID 39594744, 2024). "PRMT5 induces the phosphorylation of the epidermal growth factor receptor (EGFR), upregulates the expression of β-catenin through the EGFR/AKT/β-catenin pathway, and promotes the EMT of pancreatic cancer cells to enhance tumor migration and invasion." (PMID 36902253, 2023).
pancreatic cancer (continued). "In this study, we investigated whether inhibition of PRMT5 activity was synergistic with blockade of TGF-β1 signaling, which plays an important role in the construction of the desmoplastic matrix in pancreatic cancer and induces therapeutic vulnerability." (PMID 36765032, 2023). "We found that PRMT5 had the positive strong expression in pancreatic cancer and negative weak expression in normal pancreas." (PMID 31851779, 2020). "Mechanistic studies demonstrated that PRMT5 could epigenetically suppress FBW7 expression and elevate cMyc stability, leading to tumorigenicity and aerobic glycolysis in pancreatic cancer." (PMID 30922330, 2019). "Collectively, the results of our present study uncovered a novel PRMT5/FBW7/cMyc axis in pancreatic cancer, and targeting this axis might be a strategy for the treatment of pancreatic cancer." (PMID 30922330, 2019). "Further research into the roles of the PRMT5/FBW7/cMyc axis might assist the development of novel prognostic and treatment targets in pancreatic cancer." (PMID 30922330, 2019). "The present study demonstrated that PRMT5 epigenetically silenced the expression of the tumor suppressor FBW7, leading to increased cMyc levels and the subsequent enhancement of the proliferation of and aerobic glycolysis in pancreatic cancer cells." (PMID 30922330, 2019). "Thus, we measured the expression status of PRMT5 by immunohistochemical staining and examined its correlation with the SUVmax obtained by PET/CT imaging, which reflects glucose uptake in pancreatic cancer patients." (PMID 30922330, 2019). "They found that PRMT5 posttranslationally regulated c‐Myc stability via the E3 ubiquitin ligase FBW7, which controlled c‐Myc degradation, thus increasing c‐Myc levels and leading to the subsequent enhanced proliferation and aerobic glycolysis in pancreatic cancer cells." (PMID 40384988, 2025). "In conclusion, this study demonstrates that the combination treatment of T1-44, a PRMT5 inhibitor, and Vactosertib, a TGF-β signaling inhibitor, showed impressive synergistic results in improving survival, inhibiting cell invasion and EMT, and stimulating the apoptosis pathway in pancreatic cancer." (PMID 36765032, 2023). "In a pancreatic cancer organoid drug screening study, researchers screened 76 non-clinical compounds and found that PRMT5 inhibitor EZP015556 could be a potential candidate for MTAP-negative pancreatic cancer." (PMID 37576596, 2023). "In this study, we provide a novel notion that PRMT5 induces the phosphorylation of EGFR, and then activates phosphorylation of Akt and its downstream GSK3β, and thereby up‐regulates expression of β‐catenin to enhance the migratory and invasive motility and promotes EMT of pancreatic cancer cells." (PMID 31851779, 2020).
mantle cell lymphoma (29 papers, 2012 to 2026). Mantle cell lymphoma is a rare form of malignant non-Hodgkin lymphoma affecting B lymphocytes in the lymph nodes in a region called the ``mantle zone''. "PRMT5 deregulation has been linked to tumorigenesis and showed efficacy in in vitro and in vivo models of mantle cell lymphoma (MCL)." (PMID 28067760, 2017). "There are SAM‐uncompetitive inhibitor of PRMT5 (EPZ015666/GSK3326595) that has been shown to be an effective antiproliferative agent in mantle cell lymphoma models with of PRMT5 overexpression." (PMID 39711357, 2024). "Inhibition of PRMT5 by the small-molecule compounds GSK3203591 or GSK3326595 has been reported to act antiproliferatively on mantle cell lymphoma, both in vivo and in vitro." (PMID 35475236, 2021). "PRMT5 is highly expressed in both the nucleus and cytoplasm in transformed mantle cell lymphomas and enriched in the nucleus in patient samples." (PMID 22952863, 2012). "EPZ015666 was highly selective for PRMT5 against other protein methyltransferases; exhibited dose-dependent inhibition of SmD3 dimethylation in mantle cell lymphoma (MCL) cells; and inhibited MCL cell proliferation in vitro and MCL xenograft tumor growth in vivo." (PMID 34065983, 2021). "For instance, PRMT5, an arginine methyltransferase, is overexpressed in mantle cell lymphoma (MCL) and diffuse large B-cell lymphoma (DLBCL), underscoring the relevance of histone methylation in these diseases." (PMID 40299416, 2025). "For instance, treatment of mantle cell lymphoma (MCL) cell lines with an inhibitor of arginine PRMT5 EPZ015666 (GSK3235025) resulted in cell death due to inhibited methylation of splicing-related protein SmD3." (PMID 39528914, 2024). "Similar observations reported in mantle cell lymphoma (MCL) show that MCL cell lines with an enhanced PRMT5 expression display aberrant expressions of miR-92b and miR-96." (PMID 36358861, 2022). "The overexpression of PRMT5 has been observed in solid and hematological malignancies, e.g., mantle cell lymphoma (MCL) which depends on PRMT5 activity for their survival." (PMID 34200178, 2021). "The strongest mechanistic link currently described between PRMT5 and cancer is in mantle cell lymphoma (MCL)." (PMID 29946150, 2018). "Protein arginine methyltransferase 5 (PRMT5) is overexpressed in B-cell lymphomas, including diffuse large B-cell lymphoma (DLBCL) and mantle cell lymphoma (MCL)." (PMID 41998301, 2026). "In mantle cell lymphoma (MCL), research on PRMT5 inhibition showed that activating pro-apoptotic BCL-2 family genes such as BAX enhances cell sensitivity to venetoclax." (PMID 39685591, 2024). "Orally available PRMT5 inhibitor (EPZ015666 [GSK3235025]) inhibits SmD3 methylation and RNA splicing as well as induces antitumor efficacy in mantle cell lymphoma (MCL) cells in vitro and in vivo." (PMID 37342192, 2023). "In mantle cell lymphoma (MCL), low levels of miR-92b and miR-96 drive increased PRMT5 expression, promoting cell proliferation." (PMID 34685445, 2021). "A selective inhibitor of PRMT5, EPZ015666 (also known as GSK3235025), was reported in the treatment of mantle cell lymphoma (MCL) model." (PMID 34522232, 2021). "A selective PRMT5 inhibitor, EPZ015666, has antitumor effect via reducing proliferative role of cancer cells and tumor growth in mantle cell lymphoma (MCL) xenograft model." (PMID 36765032, 2023).